APC (APC regulator of Wnt signaling pathway)
Diseases named in the same sentence as APC in open-access papers (continued):
Sharing a sentence is not in itself a finding about the gene and the disease.
colon carcinoma (continued). "We analyzed the changes in SLC7A7 and gene mutations, acquisitions, and deletions in colon cancer, the difference in APC, TTN, KRAS, SYNE1, RYR2, and LRP1 mutations was statistically significant." (PMID 39730571, 2024). "In a preclinical study, vandetanib reduced the number of tumors induced by dextran sulfate sodium in an APC-deficient colon cancer mouse model." (PMID 38894864, 2024). "Over half of all subjects had one or more variant in the APC gene, the most common of which was APC c.3920T>A; p.Ile1307Lys, which was significantly associated with colon cancer (p = 0.03predict)." (PMID 37306523, 2023). "To reveal the roles of RAI14 in colon cancer, we knocked down RAI14 in the APC-mutated colon cancer cell lines DLD-1 and SW480 and overexpressed RAI14 in the SW480 cell line." (PMID 36934880, 2023). "USP7 functions as a WNT activator through the deubiquitination of β-catenin and promotes the growth of APC-mutated colon cancer cells." (PMID 37740002, 2023). "Aberrant WNT signaling is a key oncogenic driver in colon cancer, mostly as a consequence of mutations in Adenomatous Polyposis Coli (APC), β-catenin or axin." (PMID 36683050, 2023). "RSPO2 and RSPO3 mutations are found in approximately 10% of colon cancers and occur in a mutually exclusive manner with APC mutations." (PMID 37048063, 2023). "When knocking down β-catenin in colon cancer cell lines carrying the APC mutation, significant growth inhibition, differentiation, and reduction of proliferation occurred." (PMID 37047705, 2023). "APC was reported as mutated in colon cancer (CC) and liver cancer, where it acts as a negative regulator of canonical Wnt signaling." (PMID 37834160, 2023). "CRC is considered an aberrant Wnt pathway disease because APC mutations are the earliest alteration detected in most colon cancer cases." (PMID 36969011, 2023). "Colon cancer cell lines with APC mutations were sensitive to pyrvinium treatment, showing a decrease in cell proliferation." (PMID 37047705, 2023). "While APC was first established as a tumor suppressor in colon cancer, the loss of APC is seen in multiple different cancer types." (PMID 37108784, 2023). "Upregulation of intracellular β-catenin in SW480 and HCT116 colon cancer cells occurs due to an inactivation mutation in the APC gene and a Ser45 (CK1 phosphorylation site) deletion mutation in β-catenin, respectively." (PMID 37463866, 2023). "For example, despite activation of the WNT pathway in the majority of CIN and GS colon cancers due to APC mutations, claudin expression is highly variable, reflecting putative additional inputs." (PMID 37998722, 2023). "Human colon cancers that lack APC mutations frequently have activating mutations in CTNNB1 (β-catenin) that prevent its phosphorylation by GSK-3, demonstrating a key epistatic relationship between APC and CTNNB1/β-catenin." (PMID 37759479, 2023). "The effect of RAI14 silence on RKO cell migration was weaker than that in APC-mutated colon cancer cell lines DLD-1 and SW480." (PMID 36934880, 2023). "ICG-001 treatment lowered WNT target gene expression in colon cancer cell lines harbouring APC mutations and reduced tumour growth in a colon cancer xenograft model." (PMID 37048063, 2023). "Beyond colon cancer, APC is also mutated in around 13–15% of uterine endometrial, stomach cancer, and skin cutaneous melanoma." (PMID 37048063, 2023). "APC mutations are observed in over 80% of all Colon Cancers, which invariably exhibit cytosolic and nuclear accumulation of β-catenin." (PMID 37655825, 2023). "The WNT pathway is of central importance in colon cancer, with 80% having inactivating mutations in the APC gene that encodes a protein that promotes beta‐catenin destruction." (PMID 37584250, 2023).
colon carcinoma (continued). "IL-10 and Treg cells are suppressed after the mutation, and IL-17 promotes Apcmin/mouse (the mouse who has an express point mutation in one copy of APC gene) to develop a colon cancer." (PMID 37164974, 2023). "In conclusion, in addition to our recent report, the results demonstrate that OM-153 is a highly potent and specific inhibitor of TNKS1/2, WNT/β-catenin signaling and cell growth in the APC-mutated colon carcinoma cell line COLO 320DM." (PMID 36873622, 2022). "Later, mutations in the adenomatous polyposis coli (APC) gene were discovered to be one cause of hereditary colon cancer." (PMID 35663403, 2022). "Mutations in the tumor suppressor gene APC, found in approximately 80% of human colon cancer, disrupt intestinal stem cell (ISC) homeostasis and lead to unrestricted activation of the WNT pathway." (PMID 35572595, 2022). "The APC and β-catenin mutations are the most frequently occurred mutation types in components of the Wnt signaling pathway in colon cancer." (PMID 35494070, 2022). "About 70% of sporadic colon cancers are caused by inactivation of the tumor suppressor gene for biallelic APC, resulting in abnormal activation of the WNT/β-catenin signaling pathway." (PMID 35937946, 2022). "We have discovered that the combination of a Wnt inhibitor (PP/PPh) with a Bcl-2-family inhibitor (ABT263) is effective in killing colorectal cancer cells with APC mutations both in vitro and in colon tumor xenografts." (PMID 36860494, 2022). "In vitro cultures of colon cancer cells often present mutations either in the APC gene or in the β-catenin gene." (PMID 35267666, 2022). "Over 70% of colon cancers contain a mutation in adenomatous polyposis coli (APC) genes, which are associated with the earliest stages of colorectal carcinogenesis." (PMID 35299743, 2022). "Given a significant proportion of CRC are initiated by the loss of APC‐function, a Wnti/Bcl‐2i drug combination was also explored in a mouse xenograft model of colon cancer." (PMID 35301819, 2022). "The adenomatous polyposis coli (APC) tumor suppressor is frequently mutated in colon cancer and mouse models, and APC mutations are widely used in colon cancer research." (PMID 35954274, 2022). "Another example of somatic insertion of the LINE-1 element was observed in the APC tumor suppressor gene in several patients with colon cancer and in association with desmoid tumors or aggressive fibromatoses." (PMID 35269693, 2022). "Of the 390 colon cancer patients with SNP and transcriptome data, APC mutations were detected in 75% (293 of 390) of the tumors." (PMID 35937946, 2022). "This de novo L1Hs insertion in chromosome 5 disrupted an exon of the APC tumor suppressor gene, producing a trigger mutation that likely caused the subsequent colon cancer." (PMID 35269693, 2022). "Similar mutation mechanism has been described in just over 20 other genetic disorders as well as a somatic variant in the APC gene in colon carcinoma." (PMID 33807868, 2021). "As a consequence, ICG-001 selectively induces apoptosis in colon carcinoma cells but not in normal colonic epithelial cells, which is effective in mouse with APC mutations or nude mouse xenograft models of colon cancer." (PMID 34381360, 2021).
colon carcinoma (continued). "Accordingly, Wnt ‘super-activation’ by GSK3β inhibition (i.e., Chiron) in the APC/CTNNB1-mutated colon cancer cell lines results in a significant expansion of EpCAMlo cells and increased ZEB1 expression." (PMID 34036938, 2021). "Of note, the patient had a typical FAP course with germline variants of the APC gene and early occurrence of colon cancer combined with multiple adenomatous polyps." (PMID 34455522, 2021). "Scientists have discovered miR-142 can inhibit stem cell-like traits by targeting APC gene whose mutations are linked to colon cancer." (PMID 34381360, 2021). "KRAS, APC, and β-catenin mutations in colon cancers have been associated with poorer survival and increased tumor aggressiveness." (PMID 33917100, 2021). "Nonsense mutations in the APC gene, which are generally associated with the generation of truncated forms of APC, contribute to the development of colon cancer." (PMID 34568323, 2021). "It has been reported that certain colon cancer cells are still responsive to Wnt ligands despite the presence of pathway-activating mutations in APC or β-catenin." (PMID 34849464, 2021). "The majority of cases of colon cancer are sporadic, but a distinct marker is a somatic mutation of the adenomatous polyposis coli (APC), which appears to be a determinant early step in the development of colorectal cancer." (PMID 33814980, 2021). "A mutation of APC in colon cancer creates a truncated form of the protein that is missing the domain responsible for the interaction with Axin." (PMID 34356615, 2021). "The most common mutations in colon cancer are found in adenomatous polyposis coli (APC) and resulted in inactivated truncation forms." (PMID 34440086, 2021). "APC is a multifunctional and crucial tumor suppressor gene in the gastrointestinal tract, and mutations causing APC inactivation are found in about 80% of all human colon tumors." (PMID 34000297, 2021). "Murine models and other model animals have confirmed that heterozygosity of APC mutations similar to those seen in CRC patients produce an autosomal dominant colon cancer predisposition." (PMID 34000297, 2021). "While colon tumors are mainly predominated by frameshift and stop gains, 47.1% of APC mutations in gastric cancer are missense." (PMID 34313788, 2021). "We used mouse AK organoids established from colonic tumors developed in mice carrying Villin-CreERT2/+, lsl-KrasG12D/+, and ApcΔ716/+ alleles, since APC and KRAS mutations were observed in >80% and >40% of CRC, respectively." (PMID 34262603, 2021). "In cancers with a mutation in APC, the regulation of colon cancer cells iron stores became IRE/IRP independent and despite high iron, TFR1 and DMT1 expression increased." (PMID 34211054, 2021). "Adenomatous polyposis coli (APC) mutation is the most common (90%) genetic alteration in colon cancer patients and its downstream target, β-catenin, is highly associated with cancer cell survival and proliferation." (PMID 34361052, 2021). "Somatic mutations in APC are widely regarded as the earliest genetic lesion in 80-90% of sporadic colon cancers." (PMID 33335067, 2021). "In a future study, it will be necessary to verify the effect of eupatilin in colon cancer cells with mutations in genes such as APC, β-catenin, and KRAS." (PMID 34203665, 2021). "We have long known that human colon cancers having β-catenin mutations grow less aggressively than those with APC mutations." (PMID 34000297, 2021). "∼85–90% of colon cancer cell lines contain mutations in APC resulting in aberrant activation of WNT/β-catenin signaling." (PMID 34337362, 2021). "APC mutational inactivation is a key event in the development of colon cancer and the intestinal polyp disorder FAP." (PMID 33670833, 2021).
colon carcinoma (continued). "A connection of tumors with colon inflammation is supported by the fact that the mutational landscape of inflammation-induced colon cancer differs from the majority of sporadic colon tumors, which typically harbor mutations in APC or Ctnnb1." (PMID 34849464, 2021). "For example, APC (Adenomatous Polyposis Coli) gene mutations in patients with familial adenomatous polyposis syndrome can promote the occurrence of final colon cancer." (PMID 33719345, 2021). "The vast majority of colon cancers are initiated by mutations at the APC gene predicted to lead to constitutive Wnt signaling by β-catenin nuclear translocation." (PMID 34036938, 2021). "Since the Wnt pathway is generally activated in colon cancer cell lines due to APC mutation, the 100-fold or greater difference in sensitivity to MF-438 between CSCs and BCCs is interesting." (PMID 33430034, 2021). "More than 90% of the cases of sporadic colonic tumors harbor mutations in the core pathway components APC and/or β-catenin (CTNNB1)." (PMID 34849464, 2021). "Studies have demonstrated that mutations in the APC gene are detected in approximately 70%–80% of human colon tumors, indicating that the activation of the Wnt/beta-catenin (CTNNB1) pathway plays a crucial role in human colon tumorigenesis." (PMID 34680448, 2021). "For example, the first event in most colon cancers appears to be mutations that inactivate the APC gene, a negative regulator of Wnt signaling, leading to development of benign adenomas with mild dysplasia." (PMID 34769520, 2021). "IQ-induced mutations in the APC gene occurred in rat colon tumors but only in 2 out of 13 tumors analyzed." (PMID 34271992, 2021). "APC plays a pivotal role in β-catenin-dependent tumorigenesis, such that partial or complete loss of its function is recognized as a hallmark of many colon cancers." (PMID 32415084, 2020). "It is convinced that either polyposis or nonpolyposis syndromes can contribute to the genetic vulnerability to colon cancer, which is associated with mutation or loss of APC gene and several DNA mismatch repair genes." (PMID 32859214, 2020). "APC, a tumor suppressor gene, is the most frequently mutated gene in patients with colon cancer and influences the Wnt/β-catenin pathway." (PMID 33254149, 2020). "Up to 90% of colon cancer cases have a mutation in APC, making it an important target in colon cancer therapeutics." (PMID 33105836, 2020). "In many colon cancers, driver mutations are acquired sequentially, and common initial mutations driving dysplasia are nonsense mutations in APC, a negative regulator of the Wnt pathway." (PMID 32823838, 2020). "L1 retrotransposition can also contribute directly to cellular transformation; in colon cancers, acquired L1 insertions are known to cause driving mutations in the adenomatous polyposis coli (APC) tumor suppressor." (PMID 31892958, 2020). "The gatekeeper gene APC is a negative regulator of β-Catenin and is mutated in approximately 80% of sporadic and hereditary colon cancers." (PMID 32811441, 2020). "An increased expression of the downstream apoptotic mediators caspase 3, 7, and 9 was found in Apc-mutated colon cancer, suggesting that the loss of APC increases the apoptotic response." (PMID 33105836, 2020).
colon carcinoma (continued). "Human colon cancer with APC mutation, rendering inappropriate β-catenin stabilization and hyperactivated canonical Wnt pathway, exhibited a hereditary cancer syndrome named familiar adenomatous polyposis (FAP)." (PMID 33109217, 2020). "Further, in FAP and sporadic CRC patients, APC mutations increase autocatalytic tissue polymerization and induce tumor tissues to catalyze their own progressive growth early in colonic tumor development." (PMID 32079164, 2020). "Mice with mutations in the adenomatous polyposis coli (APC) tumor suppressor are frequently used as a tool for PPAR research in colon cancer, but also a direct function of the APC tumor suppressor on PPARβ/δ expression has been described." (PMID 32375405, 2020). "Colon cancers frequently harbor truncating mutations to APC that yield proteins with impeded function in degrading β-catenin; or oncogenic mutations to the CTNNB1 gene that remove the destruction complex phosphorylation sites in the N-terminus of β-catenin." (PMID 32486480, 2020). "GEMM for colon cancer were typically driven by APC loss and these mice develop tubular adenomas and epithelial-like tumours." (PMID 32647253, 2020). "Deactivation of checkpoint kinase 1 using antisense siRNA-mediated knockdown sensitized these APC-mutated colon cancer cells to the treatment of 5-FU." (PMID 32503256, 2020). "In both FAP and sporadic cases, mutations of APC genes are known events in the development of colonic tumors." (PMID 32079164, 2020). "Mutational inactivation of APC is one of the earliest and frequent genetic events in human colon cancers, and the majority of human sporadic colorectal cancers contain adenomatous polyposis coli (APC) mutations." (PMID 33202710, 2020). "Using cBioPortal, we queried the TCGA (PanCancer Atlas) dataset for expression of Wnt target genes in colon cancers with various categories of APC or CTNNB1 mutations." (PMID 32751567, 2020). "Constitutive β-catenin signalling due to inactivating mutations in APC or activating mutations within β-catenin itself plays a critical role in colon cancer development." (PMID 30944457, 2019). "In colon cancer, the canonical APC mutations decrease DNA methylation through upregulation of demethylases, which potentially alters the impact of RAS mutations acquired later in disease evolution." (PMID 31784538, 2019). "Sporadic colon cancers are mostly caused by genetic mutations of APC and β-catenin which results in β-catenin stabilization and formation of the β-catenin/TCF4 complex." (PMID 31608135, 2019). "These factors are required for growth of organoids derived from healthy tissue but are dispensable for the growth of colon tumor organoids because these harbor mutations (APC, CTNNB1 (β-catenin), or AXIN) that activate Wnt signaling independently of ligands." (PMID 31752287, 2019). "After acquiring consecutive mutations, mostly initiated by an inactivating mutation in the adenomatous polyposis coli (APC) gene, colon cancer stem cells arise from intestinal stem cells." (PMID 31227689, 2019). "In colon cancer, mutation of the APC tumor suppressor activates β‐Catenin/Tcf signaling, leading to transcriptional induction of c‐myc and cyclin D1 in colon cancer 13, 15 illustrating the oncogenic potential of this signal transduction pathway." (PMID 30869835, 2019). "MYC activates the transcription of LEF1 and is required for LEF1 expression in colon cancer cells and in primary colonic cells transformed by APC loss of function, a common mutation in colon cancer patients." (PMID 31623618, 2019).